MMP14 (matrix metallopeptidase 14)
Diseases named in the same sentence as MMP14 in open-access papers (continued):
Sharing a sentence is not in itself a finding about the gene and the disease.
gastric cancer (continued). "Stable over-expression of miR-584-3p resulted in increased binding of AGO2 and epigenetic markers EZH2, EHMT2, H3K27me3 and H3K9me2, and decreased binding of YY1 to MMP-14 promoter in gastric cancer cells, which was attenuated by knockdown of AGO2." (PMID 28827574, 2017). "We found that genetic ablation of the p65 subunit of NF-κB attenuated the expression of YY1 and downstream target MMP-14, shedding light on a potential approach to regulate the MMP-14 expression in gastric cancer." (PMID 28827574, 2017). "Further analysis of Gene Expression Omnibus (GEO) datasets indicated the positive correlation between MZF1 and MMP-14 levels in different gastric cancer cohorts." (PMID 27259238, 2016). "Since above evidence indicated that miR-337-3p attenuated the binding of MZF1 to MMP-14 promoter, we further investigated the effects of miR-337-3p over-expression on MZF1-facilitated MMP-14 expression in gastric cancer cells." (PMID 27259238, 2016). "We demonstrate, for the first time, that MZF1 is highly expressed and facilitates the transcription of MMP-14 in gastric cancer." (PMID 27259238, 2016). "We found a decreased expression of the epithelial markers CDH1, EpCAM, and increased expression of the mesenchymal markers CDH2, Vimentin, ZEB1, Snail, MMP14 and Twist in un-captured cells in gastric cancer cell lines AGS, SGC7901 and BGC-823." (PMID 27654478, 2016). "First, the expression of MZF1 and MMP-14 was positively correlated in gastric cancer tissues and cell lines." (PMID 27259238, 2016). "We demonstrated that MZF1 directly bound to the MMP-14 promoter to facilitate its nascent transcription and expression in gastric cancer cell lines." (PMID 27259238, 2016). "The expression of VEGF, the MMP-14 downstream gene in gastric cancer, was significantly decreased or increased in miR-337-3p over-expressing and knockdown gastric cancer cells, consistent with the MMP-14 levels." (PMID 27259238, 2016). "Taken together, these data indicate that miR-337-3p directly binds to the MMP-14 promoter to repress MZF1-facilitatd MMP-14 expression, thus suppressing the progression of gastric cancer." (PMID 27259238, 2016). "To investigate the mechanisms crucial for MMP-14 expression in gastric cancer, we first analyzed the activity of a series of MMP-14 promoter fragments." (PMID 27259238, 2016). "Stable transfection of MZF1 into gastric cancer cells resulted in enrichment of MZF1 on the MMP-14 promoter." (PMID 27259238, 2016). "Meanwhile, the miR-337-3p expression was inversely correlated with MMP-14 transcript levels in gastric cancer tissues (R = − 0.488, P < 0.001)." (PMID 27259238, 2016). "Higher MZF1 and MMP-14 levels were observed in gastric cancer cell lines than those in normal gastric epithelial cells." (PMID 27259238, 2016). "Our findings showed that miR-337-3p was an independent prognostic factor for favorable outcome of gastric cancer, and suppressed the expression of MMP-14 through repressing the enrichment of MZF1 on MMP-14 promoter in gastric cancer cells." (PMID 27259238, 2016). "Western blot, real-time quantitative RT-PCR, and dual-luciferase assays demonstrated that knockdown of AGO2 abolished the miR-337-3p-induced transcriptional repression of MMP-14 in gastric cancer cells." (PMID 27259238, 2016). "In summary, we have shown that MZF1 is highly expressed and directly binds to the MMP-14 promoter to facilitate its transcription in gastric cancer." (PMID 27259238, 2016). "Previous studies have shown that MMP-14 is highly expressed in gastric cancer, and is correlated with poor outcome of patients, suggesting the importance of MMP-14 in the progression of gastric cancer." (PMID 27259238, 2016). "Nuclear run-on assay demonstrated that stable over-expression of MZF1 increased the nascent transcript levels of MMP-14 in gastric cancer cells, than those in mock cells." (PMID 27259238, 2016).
gastric cancer (continued). "Collectively, these results indicated that miR-337-3p recognized the binding site and recruited AGO2 to repress the MMP-14 transcription in gastric cancer cells." (PMID 27259238, 2016). "Meanwhile, miR-337-3p is under-expressed and anti-correlated with MMP-14 expression in clinical gastric cancer specimens." (PMID 27259238, 2016). "Higher protein and transcript levels of MZF1 or MMP-14 were observed in gastric cancer tissues than those in normal gastric mucosa, which was in line with the results from public datasets." (PMID 27259238, 2016). "Western blot and real-time quantitative RT-PCR were applied to measure the expression levels of MZF1, MMP-14, and miR-337-3p in 90 gastric cancer specimens and normal gastric mucosa." (PMID 27259238, 2016). "We found that AGO2 was enriched surrounding the binding site of miR-337-3p within MMP-14 promoter in gastric cancer cells." (PMID 27259238, 2016). "Since AGO2 is essential for miRNA-directed implementation of silent-state chromatin modification at gene promoters, we further observed the functions of AGO2 in miR-337-3p-repressed MMP-14 expression in gastric cancer." (PMID 27259238, 2016). "In the current work, we found that TGR5 activation inhibited MMP2, MMP7 and MMP14 gene expression in gastric cancer cells." (PMID 26417930, 2015). "KLF8 activates invasion in cooperation with focal adhesion kinase (FAK) by increased transcription of matrix metalloproteinase-14 (MMP14, also known as MT1-MMP) in gastric cancer cells." (PMID 24429391, 2014). "In this study, we detected those metastasis relevant factors, including MMP7, MMP9 and MMP14, which are particularly important in gastric cancer." (PMID 24386080, 2013). "Knockdown of IGFBP3 accelerated gastric cancer cell migration and invasion and induced the expression of invasive factors including MMP14, uPA and uPAR." (PMID 24386080, 2013). "IGFBP3 inhibits the migration and invasion of gastric cancer cells, at least in part, through the MMP14 and uPA/uPAR pathways." (PMID 24386080, 2013). "In this study, for the first time, we demonstrate that VEGF functions as a downstream gene of MMP-14 in gastric cancer cells." (PMID 23394613, 2013). "To elucidate the mechanisms underlying the down-regulation of MMP-14 by sub-cytotoxic MJ, we further demonstrated that the MMP-14 transcript levels were abolished in MJ-treated gastric cancer cells." (PMID 23394613, 2013). "In this study, we demonstrated the over-expressed Sp1 and its positive correlation with MMP-14 transcription in gastric cancer tissues." (PMID 23394613, 2013). "Among prior clinical studies, high MMP-14 mRNA expression was an independent factor of both tumor invasion and lymph node metastasis in carcinoma of stomach, lung and cervix." (PMID 16776850, 2006). "MMP-2 (gelatinase A), MMP-9 (gelatinase B), MMP-7 (matrilysin) and MMP-14 (MT1-MMP) are over-expressed in human gastric cancer." (PMID 12085177, 2002). "Histone methyltransferase EHMT2, which suppresses the expression of fumarate hydratase in nasopharyngeal carcinoma, is recruited along with EZH2 by miR-584-3p in an AGO2-dependent manner to reduce matrix metalloproteinase 14 (MMP-14) expression in gastric cancer." (PMID 41154621, 2025). "This discrepancy may be explained by concomitant upregulation of MMP9 and MMP14 in gastric cancer, where increased MMP14 expression correlates with metastasis and poor prognosis." (PMID 40643467, 2025). "Indeed, in gastric cancer cells, the authors found that miR-584-3p binds to the MMP-14 promoter in an AGO2-dependent manner, leading to increased levels of the repressive histone marks H3K27me3 and H3K9me2." (PMID 35327968, 2022). "MMP-14 is highly expressed in hepatocellular carcinoma, pancreatic cancer, non-small-cell lung cancer, gastric cancer, and cervical cancer, among else, and is closely related to tumor size, type of invasion, pathological type, degree of differentiation, and metastasis." (PMID 35891968, 2022).
gastric cancer (continued). "Moreover, the controlled expression of miR-1228 in serum exosomes by inhibiting MMP-14 is expected to be an available treatment for gastric cancer." (PMID 33883305, 2021). "Therefore, the over-expression of miR-1228 inhibited the growth of gastric cancer cells by down-regulating the expression of MMP-14." (PMID 33883305, 2021). "In this study, over-expression of miR-1228 inhibited the expression of MMP-14 protein in gastric cancer cells, while suppression of miR-1228 expression increased it, which suggests that miR-1228 participates in the progression of gastric cancer by regulating MMP-14." (PMID 33883305, 2021). "Thus, this study confirms that a high MMP14 expression predicts a worse survival in gastric cancer, revealing for the first time that survival is particularly worse when PROX1 is low." (PMID 31560170, 2019). "Our findings regarding MMP-14 in the serum of gastric cancer patients agree with these studies." (PMID 30532247, 2018). "Among gastric cancer patients, the serum MMP-14 level was high in only 39 (16.3%) patients." (PMID 30532247, 2018). "Finally, MMP-14-expressing gastric cancer cell lines, studied both in mice and in vitro, showed an increased invasion and metastatic spread compared to MMP-14 knockdown versions of the cells." (PMID 30532247, 2018). "Therefore, this study aims to investigate the value of serum MMP-14 as a biomarker in gastric cancer patients." (PMID 30532247, 2018). "Serum MMP-14 levels were higher among controls than among gastric cancer patients (p = 0.002)." (PMID 30532247, 2018). "In contrast, in our study, serum MMP-14 did not serve as a diagnostic marker for gastric cancer, since the serum levels detected among controls were higher than those among our patients." (PMID 30532247, 2018). "In gastric cancer, miR‐22 could inhibit tumor growth and metastasis by directly targeting MMP14 and Snail." (PMID 29719937, 2018). "To conclude, this study suggests for the first time that high serum levels of soluble MMP-14 in gastric cancer can serve as a marker for a worse prognosis and may indicate the presence of distant metastases." (PMID 30532247, 2018). "Notably, there was positive correlation between YY1 and MMP-14 immunoreactivity in gastric cancer cases (correlation coefficient R = 0.802, P < 0.001)." (PMID 28827574, 2017). "Upregulation of MMP14 and MMP16 (MT3-MMP) is involved in EMT, and associated with the aggressiveness of human ovarian, breast and gastric cancer." (PMID 28399108, 2017). "Recent study showed that MMP-2 and MMP-14 could be candidates for molecular markers of gastric cancer." (PMID 29358963, 2017). "In this study, through an integrative approach to mine public datasets, we identified Yin Yang 1 (YY1) and miRNA-584-3p (miR-584-3p) as crucial transcriptional regulators of MMP-14 expression in gastric cancer, with their adjacent targeting sites within the MMP-14 promoter." (PMID 28827574, 2017). "Notably, mining of publicly available Gene Expression Omnibus (GEO) datasets indicated that YY1 expression was positively correlated with MMP-14 levels in different gastric cancer cohorts 17–19." (PMID 28827574, 2017). "Notably, there was a positive correlation between MZF1 and MMP-14 transcript levels in gastric cancer tissues (correlation coefficient R = 0.797, P < 0.001)." (PMID 27259238, 2016). "To address the hypothesis that MZF1 may influence the MMP-14 expression in gastric cancer cell lines, we performed the MZF1 over-expression and knockdown experiments." (PMID 27259238, 2016). "In this study, we demonstrated that MMP-14 was a novel target gene of MZF1 in gastric cancer." (PMID 27259238, 2016). "In addition, RNase H treatment, but not RNase A treatment, abolished the enrichment of AGO2 on the MMP-14 promoter in gastric cancer cells." (PMID 27259238, 2016).
gastric cancer (continued). "In addition, subcytotoxic concentrations of MJ (0.05–0.2 mM) abolished migration, invasion, and angiogenesis of gastric cancer cells through downregulation of matrix metalloproteinase 14 (MMP-14)." (PMID 24648844, 2014). "Since previous studies reveal the critical roles of MMP-7, MMP-9 and MMP-14 in the invasion and metastasis of gastric cancer, we hypothesized that MJ might influence the expression of these genes." (PMID 23394613, 2013). "Then, we sought to determine whether Sp1 played a role in regulating MMP-14 in gastric cancer cells." (PMID 23394613, 2013). "Additionally, administration of sub-cytotoxic MJ attenuated the Sp1 expression and binding to MMP-14 promoter, implying the important role of Sp1 in sub-cytotoxic MJ-induced down-regulation of MMP-14 in gastric cancer cells." (PMID 23394613, 2013). "Importantly, there was a positive correlation between Sp1 protein and MMP-14 transcript levels in gastric cancer tissues." (PMID 23394613, 2013). "Here, we showed that Sp1 bound to the MMP-14 promoter in gastric cancer cells via ChIP assay." (PMID 23394613, 2013). "Functionally, IGFBP3 could suppress the migration and invasion of gastric cancer cells, at least in part, through the regulation of those invasive factors, including metalloproteinase-14 (MMP14) and urokinase-type plasminogen activator (uPA)." (PMID 24386080, 2013). "CDK7 expression levels have been correlated with matrix metalloproteinase 14 (MMP14) in gastric cancer, and higher expression of these proteins, along with the mRNA of their genes, has been associated with lymph node matastasis of gastric cancer and worse prognosis of the disease." (PMID 36769170, 2023). "In addition, over-expression or knockdown of miR-584-3p decreased and increased the protein and transcript levels of MMP-14 in gastric cancer cells, when compared to those transfected with empty vector (mock) or negative control (anti-NC) inhibitor, respectively." (PMID 28827574, 2017). "However, miRNAs affecting the transcription of matrix metalloproteinase 14 (MMP-14) in gastric cancer remain unknown." (PMID 28827574, 2017). "Overexpressed MMP-14 in gastric cancer may enhance local cell invasion and metastasis." (PMID 29358963, 2017). "However, the transcriptional regulators of MMP-14 expression in gastric cancer still remain largely unknown." (PMID 27259238, 2016). "Since above evidence showed that Sp1 participated in the transcriptional regulation of MMP-14 in gastric cancer, we proposed that Sp1 might play an important role in sub-cytotoxic MJ-induced decrease in the migration, invasion and angiogenesis of gastric cancer cells." (PMID 23394613, 2013). "Authors of this study showed that, by impeding the binding of YY1 to the MMP-14 promoter, an AGO2–miR-584-3p complex can suppress the tumorigenesis and aggressiveness of gastric cancer cells, both in cell lines and xenograft tumors." (PMID 35327968, 2022). "MMP14 and PROX1 expressions were studied using immunohistochemistry in the patient sample and using immunoblotting and immunofluorescence in gastric cancer cell lines." (PMID 31560170, 2019). "To further explore the functional connection between MMP14 and PROX1 in gastric cancer, we silenced PROX1 in the AGS cells using two different siRNAs." (PMID 31560170, 2019). "In total, seven out of eleven gastric cancer cell lines—MKN‐28, KATOIII, MKN‐7, MKN‐74, MKN‐45, NUGC3, and OCUM‐2MD3—showed a clear inverse correlation with the MMP14 and PROX1 expression levels." (PMID 31560170, 2019). "We studied MMP14 and PROX1 expression levels in tissue samples compared with clinical data, and determined the MMP14 and PROX1 expression levels in gastric cancer cells." (PMID 31560170, 2019). "The strengths of this study include the large patient cohort with reliable follow‐up information, validation of previous results, and the exploration of the roles of MMP14 and PROX1 in gastric cancer in both laboratory and clinical settings." (PMID 31560170, 2019).
gastric cancer (continued). "More extensive laboratory experiments and analysis on other large, well‐defined patient cohorts are needed to further disentangle the functions and cross talk between MMP14 and PROX1 in gastric cancer." (PMID 31560170, 2019). "MMP14 and PROX1 expressions were studied using immunohistochemistry in the patient samples and using immunoblotting and immunofluorescence in gastric cancer cell lines." (PMID 31560170, 2019). "We then silenced PROX1 in the AGS cells to further explore the connection between MMP14 and PROX1 in gastric cancer, finding that siRNA transfection using two PROX1‐targeting siRNAs resulted in increased MMP14 protein levels in both cases." (PMID 31560170, 2019). "In gastric cancer, miR-337-3p inhibit myeloid zinc finger 1 (MZF1) induced transcriptional activation of MMP-14 through recruiting Ago2 and inducing repressive chromatin remodeling." (PMID 29471827, 2018). "In contrast, in gastric carcinoma lines, the decrease of MT1-MMP (MMP14) was observed, explained as being the consequence of a decrease in functional activity of invadopodia." (PMID 29765540, 2018). "In 80 fresh gastric cancer specimens, higher protein and transcript levels of YY1 or MMP-14 were observed than those in normal gastric mucosa." (PMID 28827574, 2017). "In clinical gastric cancer tissues, the expression of YY1 and miR-584-3p was positively or negatively correlated with MMP-14 levels." (PMID 28827574, 2017). "In the current study, our findings showed that miR-584-3p recognized its binding site to repress the enrichment of YY1 on MMP-14 promoter, resulting in decreased expression of MMP-14 in gastric cancer cells." (PMID 28827574, 2017). "Significant difference was noted among the survival curves of gastric cancer patients with low or high expression of miR-337-3p, MZF1, or MMP-14." (PMID 27259238, 2016). "miR-337-3p was an independent prognostic factor for favorable outcome of gastric cancer, and patients with high MZF1 or MMP-14 expression had lower survival probability." (PMID 27259238, 2016). "Since our previous studies have shown the functions of miR-337-3p in repressing MMP-14 transcription, we observed the effects of miR-337-3p on MMP-14 expression in gastric cancer cells." (PMID 27259238, 2016). "Matrix metalloproteinase 14 (MMP-14), a membrane-anchored MMP that promotes the tumorigenesis and aggressiveness, is highly expressed in gastric cancer." (PMID 27259238, 2016). "In clinical specimens and cell lines of gastric cancer, MZF1 was highly expressed and positively correlated with MMP-14 expression." (PMID 27259238, 2016). "In gastric cancer, IGFBP-3 has been reported to be a suppressor of migration, invasion, and the EMT through suppression of invasive factors including MMP14 and urokinase-type plasminogen activator." (PMID 27144338, 2016). "Gain- and loss-of-function studies demonstrated that miR-337-3p suppressed the growth, invasion, metastasis, and angiogenesis of gastric cancer cells in vitro and in vivo through repressing MZF1-facilitated MMP-14 expression." (PMID 27259238, 2016). "In summary, we demonstrate, for the first time, that sub-cytotoxic MJ attenuates the MMP-14 expression via decreasing the Sp1 expression and binding on MMP-14 promoter, thus inhibiting the migration, invasion and angiogenesis of gastric cancer cells." (PMID 23394613, 2013). "Sub-cytotoxic MJ attenuates the MMP-14 expression via decreasing the Sp1 expression and binding on MMP-14 promoter, thus inhibiting the migration, invasion and angiogenesis of gastric cancer cells." (PMID 23394613, 2013). "Western blot and real-time quantitative RT-PCR indicated that administration of sub-cytotoxic (0.1 and 0.2 mM) MJ resulted in a significant decrease of VEGF expression in gastric cancer SGC-7901 and MKN-45 cells, which was consistent with MMP-14 reduction." (PMID 23394613, 2013). "The mRNA levels of MMP14, uPA and uPAR were uprequlated after knockdown of IGFBP3 in gastric cancer cells." (PMID 24386080, 2013).